SMOX (spermine oxidase)
Diseases named in the same sentence as SMOX in open-access papers (continued):
Sharing a sentence is not in itself a finding about the gene and the disease.
retinal disease (2 papers, 2022 to 2024). "The upregulation of SMOX expression observed in the EAE retina is consistent with our findings in other retinal disease models." (PMID 36552864, 2022). "Studies from our laboratory have demonstrated that the oxidation of polyamines is associated with neurovascular damage in the retina, and spermine oxidase (SMOX, an enzyme in polyamine catabolism) is critically associated with neuronal damage and dysfunction in retinal disease models." (PMID 39768141, 2024). "However, no studies have investigated the impact of SMOX inhibition on inflammation and neuroprotection associated with retinal diseases." (PMID 36552864, 2022).
ulcerative colitis (2 papers, 2018 to 2021). An inflammatory bowel disease involving the mucosal surface of the large intestine and rectum. "This is consistent with the increase of SMOX mRNA levels and SMOX protein expression in inflammatory cells of patients with ulcerative colitis (UC)." (PMID 29922289, 2018). "Although no studies have reported the role of SMOX in LUAD, it has a significant correlation with chronic inflammation, such as in ulcerative colitis, prostatic intraepithelial neoplasia (PIN), and Helicobacter pylori-associated gastritis." (PMID 34393804, 2021).
Alzheimer disease (1 paper, 2025). A progressive, neurodegenerative disease characterized by loss of function and death of nerve cells in several areas of the brain leading to loss of cognitive function such as memory and language. "Supplementation of spermidine, a product of SMOX activity, demonstrated neuroprotective effects in Alzheimer’s disease, aging, neuropathy, optic nerve injury, etc." (PMID 40001462, 2025).
asthma (1 paper, 2021). "Additionally, ALDH1A3 and SMOX were also essential for childhood asthma and were enriched in the “beta-alanine metabolism” pathway." (PMID 34456632, 2021).
Atrophy (1 paper, 2020). Any weakening or degeneration, especially through lack of use. "Noteworthy, also in ALS mouse models p21 mRNA and the linear SMOX RNA show an opposite trend, suggesting a p21-mediated repression of SMOX as demonstrated in other atrophy mouse models." (PMID 33153123, 2020).
brain injury (1 paper, 2025). Acute and chronic (see also brain INJURIES, CHRONIC) injuries to the brain, including the cerebral hemispheres, CEREBELLUM, and brain STEM. "Together, these data further support the central role of SMOX in promoting pro-inflammatory responses in the aged brain following traumatic brain injury." (PMID 40563341, 2025). "Given our earlier findings that SMOX is predominantly upregulated in neurons in the aged brain, we next investigated whether the increased SMOX contributes to neuronal degeneration following traumatic brain injury and whether its pharmacological inhibition could confer neuroprotection." (PMID 40563341, 2025).
brain tumours (1 paper, 2025). "Spermidine is a polyamine, known to be increased in brain tumours including glioblastoma and medulloblastoma, although the role of SMOX in this process has not been characterised." (PMID 39915814, 2025).
Chronic colitis (1 paper, 2024). A chronic inflammatory disease of the large intestine (colon, cecum and rectum). "Loss of spermine oxidase (SMOX) could shift the composition of microbiome including increase Deferribacteres in chronic colitis and increase the risk for developing CRC." (PMID 38386206, 2024).
chronic kidney disease (1 paper, 2024). Impairment of the renal function secondary to chronic kidney damage persisting for three or more months. "Moreover, renal SMOX expression is positively correlated with kidney fibrosis and function decline in patients with chronic kidney disease." (PMID 38775007, 2024).
Cognitive impairment (1 paper, 2025). Abnormal cognition is characterized by deficits in thinking, reasoning, or remembering. "Strikingly, SMOX mRNA levels exhibited strong correlations with both motor deficits (as measured by NSS) and cognitive impairments (assessed by novel object recognition tasks)." (PMID 40563341, 2025).
demyelinating disorders (1 paper, 2025). "This study provides compelling evidence for the potential of SMOX inhibition as a therapeutic strategy in multiple sclerosis and other demyelinating disorders." (PMID 40001462, 2025).
epilepsy (1 paper, 2022). A brain disorder characterized by episodes of abnormally increased neuronal discharge resulting in transient episodes of sensory or motor neurological dysfunction, or psychic dysfunction. "Spermine oxidase, specifically oxidized spermine, is a neuromodulator of several types of ion channel and ionotropic glutamate receptors, and its deregulated activity has been linked to several brain pathologies, including epilepsy." (PMID 35204705, 2022).
Epstein-Barr virus infection (1 paper, 2022). An infection that is caused by Epstein-Barr virus. "Finally, four significant KEGG enrichment pathways were identified (P < 0.05): beta-Alanine metabolism (SMOX, HIBCH), Pathways in cancer (GLI2, AR, TXNRD3, TRAF3, FGF16), Non-homologous end-joining (MRE11), Epstein-Barr virus infection (TRAF3, PSMD13, SIN3A)." (PMID 36330154, 2022). "Finally, the results of KEGG enrichment analysis showed four significantly enriched pathways (P < 0.05): beta-Alanine metabolism (SMOX, HIBCH), Pathways in cancer (GLI2, AR, TXNRD3, TRAF3, FGF16), Non-homologous end-joining (MRE11), Epstein-Barr virus infection (TRAF3, PSMD13, SIN3A)." (PMID 36330154, 2022).
experimental autoimmune encephalomyelitis (1 paper, 2022). An autoimmune demyelinating disease of the central nervous system that is produced experimentally in animals by the injection of homogenized brain or spinal cord in Freund's adjuvant. "In the present study, utilizing the experimental autoimmune encephalomyelitis (EAE) model of MS, we determined the impact of SMOX blockade on retinal neurodegeneration and optic nerve inflammation." (PMID 36552864, 2022).
folate deficiency (1 paper, 2017). A nutritional condition produced by a deficiency of FOLIC ACID in the diet. "In summary, these findings suggest that hsa‐let‐7 g may exert its biological function in NTD cases associated with folate deficiency by regulating the expression of its target genes, such as SMOX." (PMID 28631291, 2017).
glioblastoma (1 paper, 2025). The most malignant astrocytic tumor (WHO grade IV). "Leveraging the GBmap dataset, we show that SMOX is preferentially expressed in astrocytes, raising the possibility that its expression could be linked to lineage specification in glioblastoma." (PMID 39915814, 2025). "Our study has identified two novel druggable target genes, SMOX and GABBR2, which are differentially regulated and expressed in normal and neoplastic stem cells in glioblastoma." (PMID 39915814, 2025). "SMOX and GABBR2 are novel patient-specific epigenetically regulated potentially druggable targets in glioblastoma." (PMID 39915814, 2025). "Comparative analysis of switching chromatin states between GIC and iNSC identified novel pharmacologically targetable genes, including SMOX and GABBR2 in a subgroup of glioblastoma, which could be further explored as new therapeutic approaches to counteract glioblastoma invasiveness." (PMID 39915814, 2025).
kidney injuries (1 paper, 2022). "In mice, genetically ablation of SSAT and SMOX inhibit tubular injuries and restore kidney function after AKI, suggesting a critical role of endogenous polyamine metabolism in the pathogenesis of kidney injuries." (PMID 36058905, 2022).
leukoplakia (1 paper, 2022). A white patch or plaque on a mucous membrane that cannot be characterized clinically or pathologically as any other disease. "We also found that SMOX IHC staining in leukoplakia tissues from antibiotic-treated mice was weaker than in tissues from control mice." (PMID 36046649, 2022).
melanoma (1 paper, 2023). A malignant, usually aggressive tumor composed of atypical, neoplastic melanocytes. "Moreover, melanoma secretome induces expression of a set of transcripts encoding for protein with tumor-promoting functions including CLEC17A, FR2, SMOX, TOX and ENPP1." (PMID 38239354, 2023).
muscle atrophy (1 paper, 2020). The loss of muscle tissue due to inactivity or disease. "Our study demonstrates that SMOX represents a new player in muscle physiopathology and provides a scientific basis for further investigation on circSMOX RNA as a possible new therapeutic target for the treatment of muscle atrophy." (PMID 33153123, 2020).
optic neuritis (1 paper, 2025). Optic neuritis is inflammation of the optic nerve, the nerve that carries the visual signal from the eye to the brain.The conditionmay cause sudden, reduced vision in the affected eye(s). "In summary, this study provides compelling evidence for the neuroprotective effects of SMOX inhibition in EAE-induced optic neuritis." (PMID 40001462, 2025). "Our findings suggest that SMOX inhibitors hold significant promise as a disease-modifying therapy, capable of preventing the onset of optic neuritis and mitigating further neuronal damage in cases of mild disease." (PMID 40001462, 2025).
oral cancer (1 paper, 2022). "We found that SMOX immunostaining increased with the progression of oral cancer; it was barely expressed in normal tongue epidermal tissues, but showed moderate staining in precancerous lesions and strong staining in cancerous tissues." (PMID 36046649, 2022). "Immunochemical staining proved that spermine oxidase, an effective polyamine oxidase, was upregulated in mouse oral cancer lesions." (PMID 36046649, 2022). "Although our data suggested that the increase in SMOX in oral cancer cells may be due to frequent exposure to bacteria with polyamine metabolism, the effect of microorganisms in the up-regulation of SMOX needs to be further investigated." (PMID 36046649, 2022).
ovarian carcinoma (1 paper, 2023). A malignant neoplasm originating from the surface ovarian epithelium. "SI-4650 can inhibit the activity of spermine oxidase to inhibit the development of ovarian cancer." (PMID 37895010, 2023). "Therefore, targeted therapy for spermine oxidase and mitochondrial function may be a potential research direction for treating ovarian cancer." (PMID 37895010, 2023).
renal fibrosis (1 paper, 2024). A final common manifestation of a wide variety of chronic kidney diseases characterized by glomerulosclerosis and tubulointerstitial fibrosis. "Supplementation with spermine or genetic deficiency in SMOX improves autophagy, suppresses cell senescence, and alleviates renal fibrosis." (PMID 38775007, 2024). "Supplementation with exogenous spermine or genetically deficient SMOX improved autophagy, inhibited tubular cell senescence, and ultimately alleviated renal fibrosis." (PMID 38775007, 2024). "Strikingly, gene ontology analysis confirmed that the differential proteins were significantly enriched in autophagy‐related signaling pathway, demonstrating that the SMOX/spermine metabolism is closely associated with autophagy in renal fibrosis." (PMID 38775007, 2024). "Notably, supplementation with spermine or genetically deficient SMOX improved autophagy, repressed cell senescence, and alleviated renal fibrosis." (PMID 38775007, 2024). "Collectively, these results indicate that the SMOX/spermine axis coordinates ATG5‐mediated autophagy to orchestrate renal fibrosis." (PMID 38775007, 2024). "Our results demonstrated that either spermine administration or genetically deficient SMOX enhanced UUO‐induced autophagy and attenuated renal fibrosis, reinforcing the SMOX/Spermine axis and autophagy interaction as the core mechanism of CKD." (PMID 38775007, 2024). "Collectively, the findings suggest SMOX/spermine axis is a potential novel therapy to antagonize renal fibrosis, possibly by coordinating autophagy and suppressing senescence." (PMID 38775007, 2024). "Correlation analysis revealed that SMOX expression was positively correlated with renal fibrosis, and negatively correlated with estimated glomerular filtration rate (eGFR)." (PMID 38775007, 2024). "And the ATG5/SMOX interaction may be involved in the occurrence and development of renal fibrosis through regulating spermine content." (PMID 38775007, 2024). "Since dysregulation of SMOX directly leads to changes in cellular spermine levels and our in vivo study showed that Smox+/− mice had less renal fibrosis compared with wild‐type controls, we therefore sought to determine the effect of SMOX on TGF‐β1‐induced fibrogenesis." (PMID 38775007, 2024). "Moreover, the interplay between autophagy protein 5 (ATG5) and SMOX plays a crucial role in regulating the progression of renal fibrosis by preserving intracellular spermine levels." (PMID 38775007, 2024). "Thirdly, beyond autophagy and cellular senescence, whether other signaling pathways are involved in the SMOX/Spermine axis’ effects in renal fibrosis as well as their complex interrelated mechanisms remain to be explored." (PMID 38775007, 2024). "Importantly, SMOX expression was significantly increased in kidneys with the aggravation of renal fibrosis." (PMID 38775007, 2024). "Furthermore, we demonstrated that ATG5 physically interacted with SMOX to modulate the occurrence and development of renal fibrosis through maintaining intracellular spermine levels." (PMID 38775007, 2024). "These in vivo findings suggest that SMOX/spermine axis is critical for inhibiting renal fibrosis." (PMID 38775007, 2024). "Therefore, SMOX‐mediated spermine reduction is most likely to occur primarily in TECs, thereby promoting epithelial phenotype loss and in vivo fibroblast activation, ultimately leading to ECM accumulation and renal fibrosis." (PMID 38775007, 2024). "Given that increased SMOX expression and decreased spermine level in fibrotic kidneys, as well as the anti‐fibrotic impact of spermine in mouse models of renal fibrosis, we hypothesized that elevated endogenous renal spermine content exerts favorable effects on fibrogenesis." (PMID 38775007, 2024). "Despite reports have shown the tight connection of serum spermine with CKD patients, the SMOX expression and content of spermine in kidneys and their relationship to renal fibrosis have never been directly tested." (PMID 38775007, 2024).
schizophrenia (1 paper, 2022). A major psychotic disorder characterized by abnormalities in the perception or expression of reality. "SMOX activity was also found to be increased in sera from schizophrenia patients, suggesting a key role of SMOX in the pathology." (PMID 35885061, 2022).
tauopathy (1 paper, 2024). Neurodegenerative disorders involving deposition of abnormal tau protein isoforms (tau proteins) in neurons and glial cells in the brain. "It is likely that high level of polyamine catabolism, such as SMOX-mediated spermine back-conversion to spermidine, results in oxidative stress in Tauopathy, whose detrimental effect overcomes the beneficial effect of polyamine themselves." (PMID 38740758, 2024).
tongue cancer (1 paper, 2022). A malignant neoplasm affecting the tongue. "We also found that the SMOX IHC was more densely stained in the marginal areas of the tongue cancer tissues, suggesting that cells located on the tumor surface may be exposed to external bacteria to induce SMOX expression." (PMID 36046649, 2022).
type 1 diabetes (1 paper, 2024). "However, our present study investigated the impact of SMOX inhibition using only one model of type 1 diabetes." (PMID 39768141, 2024).
vision disorder (1 paper, 2020). Any impairment to the vision. "Our results suggest that blockade of spermine oxidase signaling can be considered as a therapeutic target to limit neuronal damage and dysfunction in vision disorders." (PMID 31991839, 2020).
infection (207 papers, 2008 to 2026). The state of being infected such as from the introduction of a foreign agent such as serum, vaccine, antigenic substance or organism. "We have implicated SMOX in gastric inflammation and carcinogenesis due to infection by the pathogen Helicobacter pylori." (PMID 29922289, 2018). "Thus, the association between ETBF colonization rates of CRC patients and the expression of SMOX gene appears to be an important link between chronic inflammation caused by infection, tumor onset, and progression." (PMID 27433286, 2016). "Taken together, these findings implicate SMOX as a key component in procarcinogenic signaling and promoting disease progression in gastric carcinogenesis during infection." (PMID 39523394, 2025). "We have previously shown that spermine oxidase (SMOX), the enzyme that catabolizes the back-conversion of the polyamine spermine to spermidine, is upregulated during infection and is associated with increased cancer risk in humans." (PMID 39523394, 2025). "Of the enzymes within the polyamine pathway, the catabolic enzyme spermine oxidase (SMOX) is of particular interest as it is subject to induction in response to infection, neuronal excitotoxicity, ischemia, and oxidative stress." (PMID 36135832, 2022). "Overexpression of SMOX and SAT1, which encode the SMO and SSAT enzymes, respectively, was shown to be interconnected with infection, inflammation, and high risk of cancer." (PMID 31467634, 2019). "Spermidine and its metabolizing enzymes, i.e., spermidine/spermine-N1-acetyltransferase, spermine oxidase, acetyl polyamine oxidase, and deoxyhypusine synthase, fulfill common functions during infection in parasitic protozoa and viruses which are obligate, intracellular parasites." (PMID 37238673, 2023). "To gain insights into the anti-proliferative pro-death activity of SMOX, we analyzed the phosphorylation of H2AX histone (γH2AX), a biomarker for double-strand breaks (DSBs), in RD and JR1 cells at 24, 48, and 72 h post-infection with pSMOX or pBABE." (PMID 36755974, 2023). "After VpAHPND infection, genes in glycolysis, including HK, TPI, and ALDO, and some genes involved in amino acid metabolism, including PAST, MAT, SMOX, and UPB1, showed higher expressions in R20523 family." (PMID 37358285, 2023). "Similarly, we observed that infection of the human GEC line AGS resulted in acrolein synthesis; this was markedly and significantly reduced in cells treated with the SMOX inhibitor MDL 72527." (PMID 39523394, 2025).